ENSG00000284526 (novel protein)
Synonyms: LOC122455342
Gene: Protein-coding gene on chromosome 17 (76,563,710 to 76,569,671, reverse strand). Ensembl gene ENSG00000284526.
Genetic constraint (gnomAD): Loss-of-function variants: 0 observed, 0.25 expected, observed/expected ratio (o/e) 0, 90% interval 0 to 1.87. That is too few expected variants to judge how well the gene tolerates losing a copy. Missense variants: 8 observed, 8.37 expected, observed/expected ratio (o/e) 0.96, 90% interval 0.56 to 1.66. Synonymous variants: 4 observed, 3.9 expected, observed/expected ratio (o/e) 1.03, 90% interval 0.49 to 1.84.
Homologues: Orthologues: mouse St6galnac2 (76% identical).